SOX9 (SRY-box transcription factor 9)
Diseases named in the same sentence as SOX9 in open-access papers (continued):
Sharing a sentence is not in itself a finding about the gene and the disease.
cancer (continued). "Studies highlight the importance of SOX9 gene in its role of maintaining the cell’s undifferentiated state, in particular cancer cells." (PMID 38378837, 2024). "To gain biological insights into the possible regulatory network eliciting the activity of enhancers in modulating the expression of key pro-metastatic genes, we focused on SOX9, whose deregulation favors cancer dormancy and metastasis formation 11,22,47,48." (PMID 38503727, 2024). "At the post-transcriptional level, miRNAs and other non-coding RNAs (lncRNAs and circRNAs) regulate SOX9 expression to promote or inhibit cancer progression)." (PMID 38254873, 2024). "Additional future experiments should explore a larger panel of EMT markers and oncogenic pathways related to cancer cell dissemination in the newly established SOX9 knockdown model utilizing more complex in vitro as well in vivo models." (PMID 38275880, 2024). "Current studies have identified SOX4, SOX9, and SOX11 as transcription factors related to epithelial-mesenchymal transition (EMT), with a particular focus on SOX9 in the context of peritoneal metastasis-related cancers." (PMID 39247601, 2024). "This was particularly evident for cancer cells at the border of the invasive areas, which presented higher expression for SOX9 but lower SOX2 expression." (PMID 38275880, 2024). "It is noteworthy that SOX9 is one of the critical transcription factors involved in many diseases, including cancer, and increasing evidence shows that SOX9 is an emerging driver of cancer drug resistance." (PMID 39168971, 2024). "Stem cell-related genes such as SOX2, NANOG, KLF4, OCT4, SNAI2, SNAI1, SOX9, and others are significant promoters of stemness and contribute to increased metastasis in various cancer types." (PMID 38920995, 2024). "More interestingly, we demonstrate that dissociation of the SOX9-YAP complex is a potential approach to treat YAP-driven human cancers." (PMID 38653754, 2024). "In the current study, we observed a significant reduction in YAP’s transcriptional activity and nuclear fraction in cancer cells where SOX9 was either knocked out or knocked down." (PMID 38653754, 2024). "Recent studies have shown that Sox9 is also involved in the development and progression of various types of cancer, including breast, prostate, colon, and pancreatic cancer." (PMID 38978960, 2024). "We established three different transfections groups in QBC939 cell line to explore the biological role of SOX9 in cancer cell growth." (PMID 36854894, 2023). "Studies have focused on TGFβ1 regulation of SOX9 and/or SOX9 regulation of collagen types I and II in processes such as chondrogenesis, cancer, and other types of fibrosis." (PMID 37510994, 2023). "SOX9 has been shown to have an effect on cancer proliferation, and SOX9 knockdown has a proapoptotic effect." (PMID 36769189, 2023). "Sox9, SRY-box transcription factor 9, was found expressed abnormally in various cancers in many studies but its relevant mechanism was hardly digged out." (PMID 36854894, 2023). "Through the WNT/β-catenin pathway, SOX9 is involved in cancer cell proliferation and invasion in papillary thyroid cancer." (PMID 38132479, 2023). "Through a combination of computational analysis and experimental validation, we were able to identify three genes, SOX9, RPE65, and LSM2, as potential biomarkers for cancer risk assessment." (PMID 37183261, 2023). "The cancer stem cell population in CRC is thought to have arisen from a mutated ISC population, and that LGR5 and SOX9 are ISC markers that reside in the crypt base columnar cells of the tissue." (PMID 37950151, 2023). "According to a recent study, the imbalance of SOX9 expression is a driving factor for the occurrence and development of cancer and a boosting factor for the malignant growth of cells under different conditions." (PMID 37919693, 2023). "Most notable is the role of amino acid changes to SOX9 at position 62 (deletion of residue K), seen multiple times in cancer." (PMID 36672963, 2023).
cancer (continued). "YAP upregulates cancer stemness properties and phenotypes via Sox9, and verteporfin inhibits those characteristics." (PMID 37173920, 2023). "The collective findings support the theory that circ-PHC3 influences cancer stem cell differentiation through regulation of the miR-497-5p/SOX9 axis." (PMID 37468993, 2023). "The Cancer Genome Atlas (TCGA) database revealed that SOX9 was not only upregulated in kidney renal clear cell carcinoma but also in various types of human cancer." (PMID 37481520, 2023). "The expression of SOX9 in pan-cancers and the regulation by small molecules in cancer cell lines are unclear." (PMID 37020558, 2023). "We then examined the importance of Wnt signaling and SOX9 across a panel of CRC lines using data from the Cancer Cell Line Encyclopedia (CCLE)." (PMID 36423688, 2023). "Previous findings suggest that SOX9 expressed by ectoderm- and endoderm-derived tissues in stem cell pools potentially regulates cancer stem cells (CSC)." (PMID 37468993, 2023). "Cordycepin (CD), an adenosine analog for SOX9 expression regulation, was also conducted on cancer cells." (PMID 37020558, 2023). "For example, the genes for epithelial–mesenchymal transition (EMT), like SRY-box transcription factor 9 (Sox9) and Snail, are stimulated in certain cancers, also thanks to the stabilization of the Hira complex." (PMID 37446205, 2023). "TMEM doorways are visualized by triple immunohistochemistry, and cancer stem cells by immunofluorescence for SOX9." (PMID 37311792, 2023). "Unhinged from its normal regulation, sustained SOX9 subsequently activates oncogenic transcriptional regulators that chart the path to cancers typified by constitutive SOX9 expression." (PMID 37488435, 2023). "Apart from the roles mentioned, SOX9 was validated to involve various kinds of human diseases, including cancer." (PMID 37481520, 2023). "It suggests that SOX9 expression is upregulated in the most cancer types (15/33) as a proto-oncogene." (PMID 37020558, 2023). "In a word, the results demonstrated that overexpression of SOX9 altered the repression of cancer cell mediated by lncRNA HCG18 knockdown through PI3K/AKT pathway." (PMID 36854894, 2023). "Genes that regulate EMT such as Twist1, SOX9 and REX1 have been associated with an increased occurrence of EMT in cancer cells, leading to enhanced cell stemness, proliferation and metastasis." (PMID 36980876, 2023). "We found unexpected preferential cytoplasmic subcellular localization of transcription factor SOX9 in HGOC samples, and silencing SOX9 induced cancer stem cell death." (PMID 35159173, 2022). "SOX9 can drive cancer invasion and metastasis in multiple cancers, including prostate, breast, colon, gastric, and lung (summarized in) and is involved in promoting liver and cardiac fibrosis by stimulating ECM deposition." (PMID 35904801, 2022). "The analysis with ten articles clarified that higher expression of SOX9 was observed in GC cancers than that of normal gastric samples (OR = 16.26; 95% CI: 8.16 to 32.42; P < .00001)." (PMID 36123852, 2022). "Surprisingly, we have also observed differential expression of the F2R gene (encoding coagulation factor II thrombin receptor), which, according to the literature, can stimulate the migration and invasion of cancer cells under SOX9 influence." (PMID 35216085, 2022). "As a rule, the elevated SOX9 expression in cancer cells leads to the stimulation of cell proliferation, but for a number of tumors, it has been shown that increased SOX9 expression can inhibit cell growth and division." (PMID 35884771, 2022). "Our identification of cytoplasmic localization of SOX9 in the HGOC proposes an unidentified role of SOX9 in cell death prevention of cancer stem cells in HGOC." (PMID 35159173, 2022).
cancer (continued). "Compared to cancer adjacent normal tissues, both mRNA and the protein expression of SOX9 in CC tissue were higher." (PMID 36003340, 2022). "Gain- and loss-of-function experiments have revealed that SOX9 activates EMT during embryonic development for neural crest delamination and cardiac valve formation, and also in different types of cancer." (PMID 35205666, 2022). "As a transcription factor, SOX9 acts as a pleiotropic factor by regulating several key signaling pathways in cancers, such as the Wnt/β-catenin, TGFβ/Smad, PI3K/AKT, and mTOR signaling pathways." (PMID 35563098, 2022). "We demonstrated that the silencing of SOX9 completely suppressed cancer stemness properties in vitro and in vivo." (PMID 35159173, 2022). "Of note, KIT+, ALDH1+ and SOX2+ cancer stem cell populations harbor proliferative and epithelial-like characteristics, while CD44+ and SOX9+ cancer stem cell populations demonstrate invasive and mesenchymal-like properties." (PMID 36171192, 2022). "The interaction of stem cell factor SOX9 with RIPK1 in the cytoplasm would contribute to the suppression of cancer cell death and stemness in metastatic ovarian cancer." (PMID 35159173, 2022). "CA3 treatment (1 μM; 48 h) in PC cells reduced the protein expression levels of PAF1, YAP1, TEAD4, CD133 (cancer stem cell marker), and SOX9 (pancreatic ductal marker)." (PMID 36180487, 2022). "Thereby, AT-101 appears to target cancer stem cells by abrogating YAP1/SOX9/β-catenin signaling in addition to suppress anti-apoptotic signaling even when Bcl-2 is downregulated." (PMID 35215257, 2022). "SOX9 regulation by microRNAs, which act as repressors of gene expression, has been widely studied in different types of cancer, but less so during organ development." (PMID 36114905, 2022). "SOX2 and SOX9 are shown to interact during increased cancer stem cell content and the development of drug resistance." (PMID 35906698, 2022). "Another in vitro study showed that the exomes secreted by preadipocytes (3T3L1 cells) influenced the differentiation, stemness, and migration of the cancer cells through miR-140/SOX2/SOX9 axis, which promote the progression of cancer." (PMID 35534879, 2022). "WT mouse CRIPSCs also had higher expression of the genes related to stem cells (Psca, Atg9b, Sox2, Sox9), cell cycle (Cdk6), mammary luminal progenitor cells (Notch3 and Notch1), and cancers." (PMID 35841025, 2022). "At the cellular level, SOX9 is a pleiotropic regulator of cancer cell activity governing additional functions to its well-known function regulating quiescence and self-renewal, such as EMT and metastasis." (PMID 35205666, 2022). "Compared to normal tissues, the SOX9 mRNA expression in cancer tissues was significantly upregulated." (PMID 36003340, 2022). "We propose that cytoplasmic SOX9-mediated cell death suppression would contribute to cancer stem cell survival in HGOC." (PMID 35159173, 2022). "Meanwhile, upregulated SOX9 can enhance gefitinib resistance of lung cancer, corresponding to increased cancer cell oncogenic phenotypes and gefitinib intake." (PMID 36182943, 2022). "Key genes that contribute to gliogenesis but also contribute to stemness in GBM: Notch (cancer stem cells), Sox9, Sox4, and SHH." (PMID 35538578, 2022). "Two of these transcription factors have been linked to modulating TUBB3 expression in cancer, SOX4 and SOX9." (PMID 35573698, 2022). "Our findings suggest an unidentified function of cytoplasmic SOX9 protein in the suppression of cancer stem cell death in HGOC." (PMID 35159173, 2022). "We have previously found that the transcriptional repressor BMI1, which is an important regulator of self-renewal, linked to EMT and metastasis in different cancers including PDAC, is an effector of SOX9 activity." (PMID 35205666, 2022). "The role of SOX9 in the anticancer resistance of CSC and the association of ALDH1 and SOX9 in cancer stem-like properties has been reported by other investigators." (PMID 35159173, 2022).
cancer (continued). "The expression of the SOX9 gene is upregulated in the majority of carcinomas, whereas in BC, SOX9 expression is inhibited." (PMID 36465380, 2022). "Our analysis of carcinomas that develop upon luminal LATS1/2 deletion showed widespread expression of Sox9, particularly in expanding K8+K14+ cells." (PMID 36443313, 2022). "Several additional studies have shown that SOX9 is involved in the formation of cancer because an increase in its level is conducive to the transformation of stem cells." (PMID 34881182, 2021). "SOX factors such as SOX17 and SOX9 seem also play supporting roles in initiating human cancers by providing primitive stem-cell-like states." (PMID 34768751, 2021). "In the Oncomine database, SOX9 was also highly expressed in multiple types of cancers than healthy counterparts and it has been reported previously that higher expression of SOX9 is correlated with poor prognosis in several cancers." (PMID 34442467, 2021). "It has also been found that exosome-carried miRNAs regulating SOX9 are involved in the progression of chemotherapy resistance in cancer cells." (PMID 34881182, 2021). "Both c-Myc and SOX9 were reported to play essential roles in normal cells and frequently dysregulated in human cancers." (PMID 34922552, 2021). "The IHC score for SOX9 in the normal and cancer cells of the cancer tissue in the CC + GL group was lower than that in the CC group." (PMID 33807620, 2021). "Our results showed that SOX9 can affect the sensitivity of cancer cells to oxaliplatin by affecting the DNA damage repair." (PMID 34124145, 2021). "SOX9 is involved in multiple functions that promote cancer progression, such as proliferation and transformation, and resistance to apoptosis and chemotherapy." (PMID 33428592, 2021). "As a liver CSC marker, Sox9 has been reported to have the ability to facilitate cancer cell growth and participate in the symmetric division and asymmetric division of CSCs." (PMID 33845903, 2021). "Although expression of SOX9 was higher in various cancer types than their counterparts from the Oncomine database, the homology of SOX9 was not strictly grouped with other three SOX members." (PMID 34442467, 2021). "Here, we identified the expression of candidate markers including HMGB1, SOX9, and YAP1, implicated in the cancer development of patients with CCA using genomic datasets from GEO." (PMID 35201494, 2021). "HCC progenitor cells, which are pre-malignant actors that give rise to cancer when the liver is under chronic damage and compensatory proliferation has been activated, express SOX9." (PMID 33807672, 2021). "Analysis of clinical samples showed a positive correlation between THY1 and classical cancer stemness marker SOX9." (PMID 35071018, 2021). "Cytoplasmic SOX9 correlates with poor clinical cancer outcomes, including both shorter disease-specific survival and relapse-free survival." (PMID 33397924, 2021). "Recent evidence indicates that SOX9 participates in cancer initiation and tumourigenicity via its regulation of initiating cells, which are functionally linked with TGFβ/Smad, Notch and Wnt/β-catenin signaling activation." (PMID 34163029, 2021). "Overexpression of SOX9 significantly enhanced DNA damage repair, thus increasing the resistance of cancer cells to oxaliplatin." (PMID 34124145, 2021). "Highly upregulated expression of SOX9 is correlated with cancer progression in renal, liver, and colorectal cancers." (PMID 34442467, 2021). "Accumulating studies have demonstrated that SOX9 is also involved in the development of multiple cancers, including gastrointestinal, breast, brain, urological, and lung cancers and others." (PMID 34778027, 2021). "As a direct downstream target of beta-catenin (β-cat), upregulated SOX9 expression through constitutive β-cat activation has been found to enhance the colony-forming capacity of cancer cells from squamous cell carcinoma." (PMID 34361001, 2021).
cancer (continued). "Among them, SOX9 has been reported as an oncogene in various human cancers by enhancing cancer cell proliferation." (PMID 35201494, 2021). "SOX9 expression is elevated in numerous types of cancer, including lung, prostate, skin, brain, colorectal, pancreatic, and breast cancer." (PMID 34881182, 2021). "For example, Sox9 is expressed in other adult cells and ductal-derived Sox9 models have presented with other types of carcinomas." (PMID 34926472, 2021). "In cancer, several studies demonstrated the involvement of SOX9 in cancer formation, as the elevation of its levels favors transformation of stem cells." (PMID 31941916, 2020). "Among the differentially expressed genes, 5 (DUSP6, SOX9, DKK1, ARRDC3 and CSRNP2) were known to be associated with signaling pathways in cancer or cancer stem cells." (PMID 32231719, 2020). "We detected a significant increase in the number of β-galactosidase-positive cells in the different cancer types, revealing that SOX9 silencing promotes the induction of senescence in cancer cells." (PMID 31941916, 2020). "In this work, we found that modulation of SOX9 levels affects BMI1 expression in multiple cancer cell lines in vitro and in vivo." (PMID 31941916, 2020). "Together, these results suggest that etoposide can suppress cancer cell proliferation by promoting the degradation of SOX9 in a KEAP1‐ and CKIγ‐dependent manner." (PMID 33173725, 2020). "Mechanistically, the modulation of SOX9 changed the expression of the transcriptional repressor BMI1 in the same direction in the three types of cancer, and the expression of the tumor suppressor p21CIP in the opposite direction." (PMID 31941916, 2020). "Colonization of GF mice with a normal microbiota inhibited cancer metastasis by suppressing the SOX9 pathway." (PMID 32686598, 2020). "Immunofluorescence analysis of KIC;Rgs16::GFP tumors show GFP is co-expressed with Sox9 positive cancer cells." (PMID 33244070, 2020). "We further showed that both mmu-miR-466i-3p and mmu-miR-466 f-3p suppresses a number of genes involved in epithelial-mesenchymal transition (EMT) and stemness of cancer stem cells such as SOX9." (PMID 32686598, 2020). "The siRNA-mediated SOX9 knockdown partially confirmed these results, suggesting the need for a certain SOX9 threshold for particular cancer-related events." (PMID 33076370, 2020). "On the contrary, ectopic upregulation of SOX9 in cancer cell lines resulted in a significant increase in the percentage of p-H3 positive cells in cultures from the 3 types of cancer, as well as increased cell count." (PMID 31941916, 2020). "SOX9 is an important candidate for the cancer marker required for activation of TGF-β/Smad signalling." (PMID 33182326, 2020). "Most of the published studies reported that SOX9 as an oncogenic protein was overexpressed in various solid tumors, inducing cancer cell growth, proliferation, migration, and invasion." (PMID 32398735, 2020). "This indicates that BMI1 re-establishes the proliferative capacity of cancer cells abrogated by SOX9 knockdown." (PMID 31941916, 2020). "Altogether, these results suggest that mmu_circ_0000730 targets mmu-miR-466i-3p and promotes cancer progression by suppressing the oncogenic effects of SOX9, activating STAT3 and forming a mmu_circ_0000730/miRNAs/SOX9 axis." (PMID 32686598, 2020). "Overexpression and mutation of SOX9 increases cell proliferation, invasiveness, and metastasis in several types of cancer; nonetheless, little is known about SOX9 and its importance in cell survival in CRC." (PMID 32411238, 2020). "SOX9 has been shown to promote the stemness of cancer stem cell or cancer progression in vitro and in vivo." (PMID 32686598, 2020). "Through our studies, a subset of cancer‐associated KEAP1 mutations was found to disrupt the substrate‐recruiting function of Kelch domain to impair the ability of KEAP1 to bind and promote SOX9 poly‐ubiquitination and degradation." (PMID 33173725, 2020).